ENSG00000212532
Synonyms: LOC124900230
Gene: Small nucleolar RNA gene on chromosome 6 (51,464,690 to 51,464,765, forward strand). Ensembl gene ENSG00000212532.
Gene Ontology:
Biological process: RNA processing
Cellular component: nucleolus
Homologues: Orthologues: rat Snord66 (84% identical), mouse Snord66 (83% identical). Paralogues in human: SNORD66 (91% identical).